COL1A2 (collagen type I alpha 2 chain)
Diseases named in the same sentence as COL1A2 in open-access papers (continued):
Sharing a sentence is not in itself a finding about the gene and the disease.
cancer (continued). "In cancer zone A, Col1a2-Itga9/Itgb1 and Fn1-Cd44 interactions among cancer cells, along with Angptl4-Sdc2 signaling between CAFs 1 and cancer cells, collectively activated stromal remodeling and promoted EMT." (PMID 40723284, 2025). "Module III is enriched with genes of cancer-associated fibroblasts (CAFs) like COL1A1, COL1A2, and COL3A1, distributing spatially around cancer cells for tumorigenesis promotion." (PMID 40033360, 2025). "Emerging studies have unveiled the context-dependent roles of COL1A2 in cancer progression and metastasis." (PMID 41561769, 2025). "Among these, FAP and COL1A2 were involved in extracellular matrix remodeling and were upregulated in various cancers." (PMID 39456726, 2024). "In metastatic LNs, most ligand‒receptor pairs are related to the collagen family, which includes genes such as COL1A1, COL1A2, and COL3A1, which are markers of cancer‐associated fibroblasts (CAFs)." (PMID 39312471, 2024). "Earlier studies have also reported the association of COL1A1, COL1A2, COL3A1, and FN1 expression with OS in different other cancer patients." (PMID 38913913, 2024). "Like COL1A1, COL1A2 is involved in various cellular processes, including cell adhesion, migration, and proliferation, making it an important player in cancer biology." (PMID 38913913, 2024). "The genes COL1A2, FSTL1, LUM, and SPARC encode proteins that structurally compose the ECM and that are frequently altered in cancer, conferring a poor prognosis and invasive phenotypes." (PMID 39563861, 2024). "The non-immune cells included endothelial cells (PVALP and PECAM1), CAFs (COL1A1 and COL1A2), and cancer cells (KRT18 and VEGFA)." (PMID 38216635, 2024). "IHC staining for COL1A2 revealed similar results, further indicating minimal cancer cell infiltration and collagen fiber formation in the liver following Hepa1-6sh-Tim-1 transplantation." (PMID 39444345, 2024). "A retrospective case-control study was conducted to develop a cancer screening test based on the detection of stromal and epithelial biomarkers (COL1A2 and KRT19) in plasma." (PMID 39273514, 2024). "Recently, type I collagen is believed to be involved in carcinogenesis and abnormal COL1A2 expression has been reported in human cancers, including gastric cancer, and pancreatic cancer." (PMID 37805556, 2023). "In the 7q21–22 area of the GC chromosome, numerous genes, including SHFM1, MCM7, and COL1A2, have been identified as likely cancer candidate genes." (PMID 37594635, 2023). "In the present study, we performed expression analysis and survival analysis for COL1A2 across 33 types of human cancer, identifying its overexpression and prognostic value in COAD." (PMID 37805556, 2023). "LYZ is associated with neutrophil degranulation and host defense peptides, whereas COL1A1, COL1A2 along with HGF, TNC, and VEGFA are all part of the PI3K pathway, which plays an important role in cancer progression, and has been implicated in TNT regulation." (PMID 37955637, 2023). "COL1A1 and COL1A2 expression changes are utilized to forecast prognosis in a number of cancer types." (PMID 37396945, 2023). "Next, the prognostic value of COL1A2 expression for the 17 types of cancers were estimated, covering two prognostic indicators consisting of overall survival (OS) and disease-free survival (DFS)." (PMID 37805556, 2023). "In the present study, we first performed pan-cancer expression analysis of COL1A2 in 33 types of human cancers based on TIMER database and integrated data combined TCGA with GTEx." (PMID 37805556, 2023). "We performed the pan-cancer analysis of COL1A2 expression in 33 types of human cancers from TIMER database and integrated data combined TCGA with GTEx." (PMID 37805556, 2023). "It was observed that COL1A2 was remarkably downregulated in 8 cancer types (i.e. ACC, CESC, KICH, LAML, PRAD, SKCM, THCA, and UCEC)." (PMID 37805556, 2023).
cancer (continued). "Our present data conforms to the construction of hsa-miR-552-3p-COL1A2 interaction, which paves the way for further cancer therapeutics." (PMID 37805556, 2023). "A total of 17 human cancer types with higher COL1A2 levels were selected for prognostic prediction analysis, demonstrating that higher COL1A2 expression indicated unfavorable prognosis in COAD." (PMID 37805556, 2023). "Collagen type I α 2 (COL1A2) is a major component of collagen type I. Recently, abnormal COL1A2 expression has been reported in human cancers." (PMID 37805556, 2023). "Previous studies provided evidence supporting the crucial role of COL1A2 in initiation and progression of multiple human cancers, including COAD." (PMID 37805556, 2023). "There was a notable trend toward lengthening of the 3’UTR in cancer cells (P = 5.59 × 10−20), with COL1A2 emerging once more as the most prominent finding (Pcorr=7.48 × 10−47, 61% change)." (PMID 38012143, 2023). "Previously, other studies proposed COL1A1, COL1A2, and COL4A1 as candidate diagnostic markers for this cancer." (PMID 38041130, 2023). "Previous studies have demonstrated the involvement of COL1A2 in the cancer process, which can be both stimulatory and inhibitory." (PMID 36057263, 2022). "It tended to increase the COL1A2 expression at advanced cancer stages (stage 1 < stage 2 < stage 3) and COL1A2 expression increased along with the nodal metastasis status (N0 < N1 < N2)." (PMID 36057263, 2022). "Intriguingly, the promoter methylation level of COL1A2 decreased with the development of cancer stages (stage 4 < stage 3 < stage 2 < stage 1) and nodal metastasis status (N2 < N1 < N0)." (PMID 36057263, 2022). "One of five up-regulated genes, COL1A2, is a subtype of Type I collagen, which can be produced by stromal fibroblasts and cancer cells." (PMID 33543230, 2021). "Association between clinico-pathological features of TSCC and non-cancer (A) COL1A2, (B) CRNN and (C) DCN immunohistochemical staining." (PMID 33889206, 2021). "Two more (COL18A1 and COL1A2) were collagen genes possessing inhibitory effects on cancer cell proliferation." (PMID 32610656, 2020). "Both COL1A1 and COL1A2 were significantly upregulated in cancer samples compared with normal samples." (PMID 31409759, 2019). "miR-29c-3p expression level was markedly lower but COL1A1 and COL1A2 expression levels were higher in cancer samples than that in normal samples." (PMID 31409759, 2019). "qPCR showed that DUXAP8, DUXAP9, COL1A1 and COL1A2 were significantly upregulated in renal cell carcinoma cancer samples compared with normal controls whereas miR-29c-3p expression in cancer tissues was decreased." (PMID 31409759, 2019). "While COL27A1, COL1A2, and COL5A3 are encoded ECM components, experiments have found that the upregulation of COL1A2 in cancer can serve as a molecular basis for metastasis development." (PMID 31660262, 2019). "Expression of DUXAP8, DUXAP9, COL1A1 and COL1A2 were significantly increased in cancer samples compared to normal controls while miR-29c-3p expression was decreased." (PMID 31409759, 2019). "Two collagen I proteins (COL1A1, COL1A2) were found significantly upregulated in cancer group compared to normal tissue." (PMID 30175151, 2018). "The role of type I collagen, composed of collagen type I alpha 1 (COL1A1) and collagen type I alpha 2 (COL1A2), has been studied in several cancers." (PMID 27894325, 2016). "Recently, similar to the expressions of other members of the collagen family which is believed to be involved in carcinogenesis, abnormal expression of COL1A1 and COL1A2 has been reported in several cancers." (PMID 27894325, 2016). "Collagen production of carcinoma cells decreases during oncogenic transformation; and, hypermethylation of COL1A2 was confirmed in several CRC cell lines (HCT 116, SW480, and SW620) as well as in primary CRC tissues." (PMID 26482433, 2015).
cancer (continued). "At least 50 genes in our list are already known to be regulated by DNA methylation, such as those encoding cancer antigens (a set of MAGE and GAGE), H19, S100A4, IGFBP4, UCHL1, COL1A2, CLU, FN1, and TGFBI." (PMID 19234609, 2009). "However, the expression patterns of COL1A1 and COL1A2 in malignant tumors remain a matter of debate." (PMID 41463322, 2025). "Furthermore, fibroblasts exposed to CC cells typically undergo conversion to cancer-associated fibroblasts (CAFs), as evidenced by increased CAF markers (e.g., ACTA2, FAP, COL1A2, VIM)." (PMID 40055606, 2025). "In the osteoblasts_Gapd2 subpopulation, pathways such as proteoglycans in cancer (Col1a1, Col1a2, Hcls1, Hif1a, Stat3, Vav1), IL-17 signaling (Mmp13, Mmp3, S100a9, Ccl7, Cebpb), and ECM–receptor interaction (Col11a2, Col1a1, Ibsp, and Tnn) were activated (p < 0.05)." (PMID 41459160, 2025). "Cancer cells could lose the Col1a2 gene and accelerate PDAC development by promoting CD4+ cells, which aggravate immunosuppression and deplete CD8+ cells." (PMID 40427098, 2025). "Emerging research has shed light on the role of COL1A2 in different cancer types." (PMID 38913913, 2024). "The high-throughput proteomics analysis revealed differential expressions of Acsl1, Plin1, Dbil5, Plin4, Col12a1, Col1a1, Col5a3, Col1a2, and Dcn, which are associated with the PPAR signaling pathway, protein digestion and absorption, and the protein glycan pathway in cancer." (PMID 36874004, 2023). "Based on the ceRNA hypothesis, predicted LncRNAs had positive correlations with COL1A2 expression and played a role of cancer promotion in COAD." (PMID 37805556, 2023). "Notably, as expected, the COL1A1+/COL1A2+/IGFBP2+ fibroblast-like cells especially MSC-like-c2 present strong interactions with malignant tumor cells (MTC), which confirms our observation from in-house data." (PMID 37479733, 2023). "The prognostic values of COL1A2 for 17 cancer types of interest were estimated from GEPIA database." (PMID 37805556, 2023). "Considering the limited samples of normal tissues in TIMER, the differential expression of COL1A2 between cancers and normal tissues was further validated in the integrated databases combined The Cancer Genome Atlas (TCGA) with The Genotype-Tissue Expression (GTEx)." (PMID 37805556, 2023). "As expected, we identified that the upregulation of three collagen genes (COL1A1, COL3A1, and COL1A2), BTG2, and JUNB might be responsible for the radiation-associated secondary cancers in patients with BCa." (PMID 35274048, 2022). "We firstly analyzed the expression levels of COL1A2 among various cancer types." (PMID 36057263, 2022). "The COL1A2 expression tended to increase along with cancer stages and nodal metastasis status in COAD, while the promoter methylation levels of COL1A2 might negatively related to its mRNA expression." (PMID 36057263, 2022). "We then checked the expression of the canonical cell-type markers: cancer/epithelial cell marker genes (Cdh1, Krt18, and Krt5); mesenchymal cell marker genes (Col1a1, Col1a2, and Col3a1); immune cell marker genes (Ptprc, Cd68, and Csf1r); and endothelial cell marker genes (Pecam1, Emcn, and Cdh5)." (PMID 34497807, 2021). "This is suggestive that COL1A2 may contribute to the formation of various cancers by modulating cell proliferation and migration." (PMID 26482433, 2015). "Four genes (DAB2, DCN, CELF2 and COL1A2) have appeared previously in cancers." (PMID 22867264, 2012). "Previous studies have reported that COL1A1 and COL1A2 could enhance cancer progression." (PMID 31409759, 2019). "Interestingly, these two modules contain three common mRNAs (EMILIN1, COL1A2, ENC1) and one of them (COL1A2) is related to cancer, suggesting that these modules (e.g. modules 15 and 17, modules 31 and 32 in OV) with many overlaps of mRNAs are more likely to have similar biological functions." (PMID 30732558, 2019). "However, the expression levels of COL1A1 and COL1A2 in malignant tumors remain controversial." (PMID 27894325, 2016).
cancer (continued). "This switch from a predominantly proliferative phenotype in low-grade cancer to an invasive phenotype in higher-grades may explain why genes (COL1A2 and SPARC) coding for extracellular matrix (ECM) proteins are independently upregulated in higher-grade stroma but not in low-grade stroma." (PMID 27152194, 2016). "Previous studies have also reported dysregulation of COL1A1, COL1A2, COL3A1, and FN1 promoter methylation in various cancers." (PMID 38913913, 2024). "A CAF subpopulation which highly expressed extracellular matrix (ECM) remodeling genes (MMP11, CTHRC1 and COL1A2) was annotated as matrix CAF (mCAF), resemble the previously reported mCAFs in cancer data." (PMID 39703515, 2024). "RNA sequencing from the SCANB and TCGA data sets was utilized to assess the expression of COL1A1 and COL1A2 in HER2+ and ER+/PR+ cancers." (PMID 38102637, 2023). "The “Proteoglycans in cancer” pathway was also exclusively enriched in AA-SScL fibroblasts, driven by the upregulation of IGF2, DCN, LUM, COL1A1, COL1A2, and the receptors KDR and TLR4." (PMID 36835058, 2023). "ER−/PR-cancers exhibited significantly (p < 0.0001) lower expression of COL1A1 and COL1A2 than ER+ tumors." (PMID 38102637, 2023). "Particularly, the positive correlations of PODNL1 expressions with such collagens as collagen type 1 alpha 1 chain (COL1A1), COL1A2 and collagen type V alpha 1 chain (COL5A1) were found in over 30 types of cancers." (PMID 37504302, 2023). "KRT19, CEA, COL1A2, and COL11A1 expression levels were much higher in cancer patients (KRT19 = 66.04 ± 14.29-fold; CEA = 245.81 ± 84.63-fold; COL11A1 = 47.80 ± 7.51-fold; COL1A2 = 40.64 ± 6.00-fold)." (PMID 36834987, 2023). "Further, COL1A1, COL1A2, COL6A1, COL6A3, and SDC1 were upregulated in late-stage compared with early-stage patients in four cancer types." (PMID 38002057, 2023). "Among them, COL1A1, COL1A2, MT-CYB, CCT5, and PAPPA have been reported to be closely related to cancer." (PMID 35360863, 2022). "In post-treatment tumors, genes such as FOS, JUNB, COL1A2, and DUSP1 have shown to favor cancer proliferation and invasion and were predominantly expressed compared with pre-treatment tumors." (PMID 36505794, 2022). "What's more, it is well known that PI3K-Akt signaling pathway (COL1A2, COL1A1, etc.)plays a vital role in the cell cycle and is activated in various cancers, including GAC." (PMID 35726219, 2022). "In this study, we explore the expression of CRNN, COL1A2 and DCN in a well-characterised bank of non-cancer disease and pN− and pN+ TSCC tissues with extensive records on use of addictive agents." (PMID 33889206, 2021). "On the contrary, both reference marker proteins COL1A2 and DCN showed a Low cytoplasmic expression in 38 (79.2%) and 44 (91.7%) non-cancer patients." (PMID 33889206, 2021). "As an example, some collagen isoforms inhibiting cancer cell proliferation, i.e., Collagen type XVIII alpha 1 chain (COL18A1) and collagen type I alpha 2 chain (COL1A2), were downregulated." (PMID 32610656, 2020). "Another interesting pathways activated in both cancer cell lines is the extracellular matrix organization which involves up-regulation of different collagen genes like (COL1A1, COL1A2, COL3A1), and matrix metallopeptidase like (MMP8, MMP14)." (PMID 25077705, 2014). "When PanIN samples were compared to PDACs, the most commonly up-regulated genes in the cancers were POSTN, COL1A2, SULF1, FN1, IGHM, VCAN and XIST, and these down-regulated were PGC and PPY." (PMID 23372777, 2013). "In cancer zone A, cancer cells primarily communicated through the COLLAGEN pathway via ligand–receptor interactions, including Col1a1-(Itga9+Itgb1), Col1a1-Cd44, Col1a2-(Itga9+Itgb1), and Col1a2-Cd44, with Col1a2-(Itga9+Itgb1)/Cd44 showing the strongest interaction strength." (PMID 40723284, 2025).
cancer (continued). "Module III represents CAFs expressing COL1A1, COL1A2, and COL3A1 enriched in the cancer regions, whereas module IV identifies a subset known as myofibroblasts (myCAFs) (COL12A1, THBS2) that mainly contribute to extracellular matrix remodeling and growth and metastasis of cancer cells." (PMID 40033360, 2025). "Moreover, we observed an increased expression of COL1A2 and KRT19 in cancer patients with an advanced stage of the disease." (PMID 39273514, 2024). "In a previous study, our group concluded that the detection of COL1A2 and KRT19 mRNA in the extracellular vesicles (EVs) of patients with advanced malignant solid tumors could be a valid and reliable neoplastic detection method." (PMID 39273514, 2024). "Functional analysis indicated that the highly-expressed FAP in these cancers could affect extracellular matrix organization process and interacted with genes like COL1A1, COL1A2, COL3A1 and POSTN." (PMID 37325617, 2023). "There was no statistical significance for COL1A2 to predict prognosis of patients in other cancer types." (PMID 37805556, 2023). "However, 6 types of cancer tissues (i.e. BLCA, KIRP, LUAD, OV, PCPG, and UCS) shared the same level of COL1A2 expression with corresponding normal controls." (PMID 37805556, 2023). "COL1A2 expression was only analyzed in eleven cancer individuals due to the lack of sample and the impossibility of reproducing replicates in the remaining oncological patients." (PMID 36834987, 2023). "From our data, the promoter methylation of COL1A2 was significantly related to age, cancer stage, and nodal metastasis status, but had no notable relation with gender, weight, and histological subtypes." (PMID 36057263, 2022). "We found a consistent positive correlation between fibroblast proportions and expression of collagen genes belonging to fibril-forming (COL1A2) and microfibrillar (COL6A1, COL6A2 and COL6A3) subfamilies across nine cancer types, the exception being KIRC and LGG." (PMID 36321857, 2022). "We have observed the elevated mRNA level of the COL1A2 in COAD in the earlier section, and then we evaluated the COL1A2 expression in COAD based on various clinicopathological characteristics like age, gender, weight, histological subtypes, cancer stage, and nodal metastasis status." (PMID 36057263, 2022). "Similarly, fibroblast-like cancer cells (C10) and endothelial cell-like cancer cells (C11) were identified based on the specific expression of fibroblast markers (DCN, COL1A2 and COL6A3) and endothelial cell markers (PCAT19, VWF and PLVAP)." (PMID 36451812, 2022). "The imbalance of α1(I) and α2(I) collagen owing to the lack of COL1A2 has been reported in some orthopedic disorders and carcinomas." (PMID 35743254, 2022). "The genome-wide co-expression analyses showed that the expression levels of collagen genes (COL1A1, COL1A2, COL5A1, COL5A2, COL8A1 and COL8A2) and LincRNAs (Linc01614 and Linc01711) were significantly positively correlated with PODNL1 expressions in various cancers." (PMID 37504302, 2023). "Nevertheless, the prognostic role of COL1A2 and the actual significance across the various clinicopathological parameters such as age, gender, weight, histological subtypes, cancer stage, and nodal metastasis status in COAD have not been systemically studied yet." (PMID 36057263, 2022). "In addition, AMG900 treatment in cancer cells suppresses most of the genes in the TPX2/AURKB subnetwork but not in the COL1A2 subnetwork." (PMID 35332150, 2022). "Therefore, the use of COL1A2 in combination with the KRT19 marker could contribute to the diagnosis of various types of cancer, regardless of stage." (PMID 39273514, 2024). "The results indicated that, compared to adjacent non-cancerous tissues, the H-scores of CDK1, STAT1, COL1A2, and COL1A1 in cancer tissues were significantly elevated, with statistical significance (P < 0.05)." (PMID 39911265, 2025).